ZNF781 (zinc finger protein 781 (pseudogene))
Description:
May be involved in transcriptional regulation.
Synonyms: FLJ37549
Gene: Transcribed unprocessed pseudogene on chromosome 19 (37,668,579 to 37,676,393, reverse strand). Ensembl gene ENSG00000196381.
Subcellular location: Nucleus
Genetic constraint (gnomAD): Missense variants: 321 observed, 409.28 expected, observed/expected ratio (o/e) 0.78, 90% interval 0.71 to 0.86. Synonymous variants: 115 observed, 139.57 expected, observed/expected ratio (o/e) 0.82, 90% interval 0.71 to 0.96.
Diseases named in the same sentence as ZNF781 in open-access papers:
ZNF781 is named in the same sentence as 4 diseases in open-access papers, as found by Europe PMC text mining. Sharing a sentence is not in itself a finding about the gene and the disease.
ZNF781 shares sentences with these, for which no sentence is quoted: cancer (1 paper); colorectal adenoma (1); lung carcinoma (1); lung fibrosis (1).